NLRP3 (NLR family pyrin domain containing 3)
Diseases named in the same sentence as NLRP3 in open-access papers (continued):
Sharing a sentence is not in itself a finding about the gene and the disease.
tumor (continued). "To examine whether CASP1 modulates ODBP in NLRP3 inflammasome-dependent manner, we obtained Nlrp3−/− mice and found that, while the mice lacking NLRP3 had less weight gain with HFD than WT mice, NLRP3 deficiency had no significant impact on tumour growth in DIO or normal-weight mice." (PMID 27708283, 2016). "Moreover, when binding to P2X7 receptors on DCs, ATP stimulates the assembly of NLRP3 inflammasome, and initiates a series of downstream events that ultimately result in the production and release of IL-1β, a cytokine required for the priming of IFN-γ producing tumor-specific CD8+ T cells." (PMID 26881822, 2016). "It was even proposed that the anti-tumor immunity resulting from chemotherapy may be mediated by ATP release from tumor cells and the activation of the NOD-like receptor family, pyrin domain containing 3 (NLRP3) inflammasome, thus suggesting the participation of the purinergic receptor P2X7." (PMID 26295158, 2015). "Another study with a similar focus reported the correlation of NLRP3 levels with OSCC tumour progression, tumour stage, lymph node involvement and metastasis." (PMID 41440367, 2025). "We showed that deletion of NLRP3, but not AIM2, phenocopied caspase-1/IL-1β dependent tumor progression in vivo." (PMID 36439171, 2022). "Our data suggested that, while anti-CTLA4-mediated-specific anti-tumor response was maintained by NFAT5 knock out, non-tumor-specific (generalized) salt-mediated NLRP3 pro-inflammatory responses were abrogated by NFAT5 knock out." (PMID 35741331, 2022). "Indeed, our results point to decreased frequencies of GMPs in the BM of Nlrp3-/- mice, which may be a result of the reduced inflammation due to tumor regression or could be explained by an intrinsic effect due to the absence of NLRP3, which may imprint on MDSC generation and subset differentiation." (PMID 36032139, 2022). "In different murine tumor models, NLRP3 plays a role in the migration of MDSCs to the TME, where MDSCs suppress antitumor CTL responses independent of NLRP3 and induce unresponsiveness to DC vaccination." (PMID 32733461, 2020). "Finally, our results show that tumor tissues in GBM patients highly express IRF3 and IRF7, encoding interferon regulatory factors that can lead to the transcription of caspase-11, which is important for noncanonical NLRP3 inflammasome activation, via activation of the JAK/STAT pathway." (PMID 31133717, 2019). "Mechanistically, these pseudoviruses activate the NLRP3 and AIM2 inflammasomes, leading to caspase-1-mediated tumour regression that is dependent on neither cytotoxic T lymphocytes nor humoral immune response." (PMID 28397782, 2017). "Collectively, this evidence confirms a role for NLRP3 inflammasome and its components in OSCC progression and metastasis; however, these studies relied mostly on cell line models, which can not fully replicate the complex tumour environment." (PMID 41440367, 2025). "Therefore, in tumor-bearing mice, the absence of NLRP3 in Th17 cells enhances CD8+ cell activity and inhibits tumor growth." (PMID 40195474, 2025). "Consequently, the absence of NLRP3 expression in Th17 cells from tumor-bearing mice enhances CD8 + T-cell effectiveness, ultimately inhibiting tumor growth." (PMID 40195474, 2025). "Although these studies demonstrated that periodontal pathogens can modulate NLRP3 expression in vitro and in vivo mouse models, they did not explore the role of AIM2 in tumour growth in vivo or examine AIM2 activation in response to bacteria-induced DNA damage." (PMID 41440367, 2025). "Additionally, the protein expression of NLRP3 and ASC was noticeably higher in tumor cells compared to normal cells and substantially increased after anti-tumor drug treatment." (PMID 39433537, 2024). "Meanwhile, the mRNA and protein expression levels of NLRP3, caspase 1, GSDMD, IL-1β and IL-18 in H(FMT) group were higher than that in T(FMT) group, while there were no noticeable difference between T(FMT) group and tumor model group." (PMID 40046008, 2024).
tumor (continued). "Unlike NLRP3, NLRP1 is positively correlated with high degree of immune cells infiltration that enhances the immune microenvironment of tumours, thereby improving patient prognosis in tumours, such as in LUAD." (PMID 39318060, 2024). "Similarly, in the absence of NLRP3, numbers of activated NK cells were increased with more IFN-γ secretion and killing of tumor cells to reduce B16F10 lung metastasis." (PMID 36605187, 2022). "Three significant up-regulated genes which had the presence of antibody-specific, immunohistochemistry-based protein expression on tumor-infiltrating lymphocytes (TILs) in tumor specimen, but not in normal lymphoid tissue, were selected including CLEC4A, C5AR1, NLRP3." (PMID 36323738, 2022). "Moreover, compared to wt mice, a significant increase in inflammatory features, tumor multiplicity, and max tumor size was found in AOM-DSS-treated Nlrp3−/− mice, but not in Nlrc4−/− mice." (PMID 29868004, 2018). "This conflicts with the findings of Zheng and Liu, who discovered higher expression of NLRP3, ASC, caspase‐1, and IL‐1B in lymph node‐positive PDAC cases; however, it is worth noting that their study included only stage I–II tumors and segmentation of tumor cells from stroma was not performed." (PMID 39969214, 2025). "Whereas this effect was mostly dependent on NLRP3, not Aim2, inflammasome, since knockout of Nlrp3, Asc, or caspase‐1 but not Aim2 through CRISPR‐Cas9 technique in DC2.4 cells markedly decreased the protein level of IL‐1β induced by the Arf1‐ablated tumor cells." (PMID 37786300, 2023). "However, whether MEG3/NLRP3 axis induces pyroptosis of TNBC and whether it mediates the anti-tumor effect of DDP in TNBC has not been reported yet." (PMID 34326697, 2021). "Based on our results that IL1β expressed preferentially in a group of tumours showing strong TXNIP nuclear expression in supporting endothelial cells indicates that the IL1β expression is mediated through the NFkB pathway, rather than direct activation of NLRP3 inflammasome." (PMID 34433833, 2021). "Although cancer cell-derived factors leading to astrocytic NLRP3 inflammasome activation have not been identified, several molecules might be responsible for this phenomenon, including released TGF-β, soluble CD44, extracellular mitochondrial DNA or ATP from dying tumor cells." (PMID 37749707, 2023). "However, in an already established tumor, the maturation of myeloid cells to macrophages is blocked by multiple factors and mechanisms, such as tumor-derived growth factors (STAT3, IRF8, C/EBPβ, Notch, adenosine receptors A2B signaling, NLRP3), hypoxia, and negative feedback loops." (PMID 34557407, 2021).
cancer (574 papers, 2012 to 2026). A tumor composed of atypical neoplastic, often pleomorphic cells that invade other tissues. "The role of the NLRP3 inflammasome, particularly activation associated with chronic inflammation and cancer progression, involves increased cytokine production and creation of a protumorigenic environment." (PMID 42222687, 2026). "More preclinical and clinical research is therefore needed to identify the best subgroup of cancer patients who will benefit from NLRP3 inhibition with common cardiovascular and cancer risk." (PMID 40069106, 2025). "NEK7 is specifically involved in the regulation of NLRP3 inflammasome activation, which is associated with many diseases including cancer." (PMID 40076620, 2025). "The NLRP3 inflammasome, which processes pro-inflammatory cytokines IL-1β and IL-18, has been implicated in cancer-related inflammation, and preliminary data indicate that dietary polyphenols can inhibit inflammasome activation." (PMID 41226270, 2025). "The positive correlation between NLRP3 inflammasome and cancer stem cells (CSCs) markers revealed that NLRP3 was associated with the carcinogenesis and CSCs self‐renewal activation." (PMID 40135589, 2025). "The persistent activation of the NLRP3 inflammasome is associated with the induction of chronic inflammation, which is widely recognized as a significant risk factor for cancer development." (PMID 40718836, 2025). "A large number of research reports focusing on GC and NLRP3 are related to cancer secondary to gastritis caused by Helicobacter pylori." (PMID 38182564, 2024). "A pan cancer bioinformatic analysis of the NLRP3 inflammasome, which did not include OC, identified 30 genes potentially associated with NLRP3 inflammasome expression." (PMID 39516433, 2024). "NLRP3 inflammasome activation leads to the processing and secretion of the pro-inflammatory cytokines IL-1β and IL-18, and polymorphisms or mutations in NLRP3 have been linked to different types of cancer." (PMID 38334625, 2024). "Another study highlighted that NLRP3 has a strong association with immune infiltration and cancer prognosis." (PMID 38182564, 2024). "CLIC3 is known to activated the NLRP3 inflammasome, which can sense different pathogens or danger signals, and its overexpression has beeb linked to immune evasion in cancer cells." (PMID 39295873, 2024). "All these results suggested that NLRP3-caspase signaling axis was activated in ULK1 deficiency cancer cells." (PMID 39215364, 2024). "In cancers such as colon and breast, the inflammatory mediators released by the NLRP3 inflammasome have been associated with increased cancerous growth and metastasis." (PMID 39769450, 2024). "The NLRP3 inflammasome has been associated with the regulation of intestinal homeostasis, with its activation linked to inflammation-induced cancer." (PMID 39769450, 2024). "It does this by causing NLRP3 inflammasome activation and boosting our body’s defenses against infections and cancer." (PMID 39511430, 2024). "Knockdown or inhibition of NLRP3 activation has been shown to increase colonic inflammation, indicating a potential therapeutic avenue for managing colitis-associated cancer." (PMID 39769450, 2024). "Another interesting finding comes from NLRP3, one of the key factors mediating the PANoptosis signaling pathway, which has now been shown to be strongly associated with cancer." (PMID 38553639, 2024). "Higher NOD-like receptor (NLR) family pyrin domain-containing 3 (NLRP3) inflammasome levels in cancer cells are linked with increased HIF-1α expression." (PMID 38904007, 2024). "Further, several studies have indicated that overactivation of the NLRP3 inflammasome has been linked to cancer progression." (PMID 39769450, 2024). "The association of STAT3 with cancer growth has been documented, and the activation of NLRP3 inflammasome in a cancer microenvironment positively affects cancer growth." (PMID 37047051, 2023).
cancer (continued). "For instance, breast cancer growth and metastasis were boosted by the NLRP3 inflammasome produced by cancer-associated fibroblasts." (PMID 36902299, 2023). "More research is needed to understand the relationship between genetic variants or variable expression of the NLRP3 inflammasome and cancer clinical characteristics." (PMID 37715239, 2023). "The rs10733113 polymorphism in the NLRP3 gene has also been studied in the context of inflammatory bowel disease and psoriatic arthritis, although its relationship with cancer remains to be studied at length." (PMID 37885032, 2023). "Persistently active NLRP3 inflammasomes are associated with some human cancers and chemoradioresistance." (PMID 37107298, 2023). "As abnormal NLRP3 inflammasome activation has been linked to cancer initiation, there is a great deal of clinical interest in the development of potential NLRP3 inflammasome inhibitors." (PMID 37715239, 2023). "Dysregulation of NLRP3 inflammasome activation is a major causative factor for chronic inflammatory, metabolic, and neurodegenerative diseases as well as cancer." (PMID 37854633, 2023). "Recent studies have shown that NLRP3 inflammasome is associated with tumorigenesis of multiple types of cancer." (PMID 37524704, 2023). "Studies have shown that although the role of inflammasome in cancer is unclear still needs to be studied in depth, it is clear that abnormal NLRP3 inflammasome activation is associated with tumorigenesis." (PMID 37082731, 2023). "In most of the cancer cell lines analyzed, including cell lines reported to carry NLRP3 mutations, the NLRP3 protein was barely detectable, whereas ASC or caspase-1 was variably expressed." (PMID 36746533, 2023). "NLRP3 is the most widely studied inflammasome and has been linked to the etiology of several disorders, including cancer." (PMID 37893079, 2023). "TAK1 inhibitors' dual function of causing cancer cell death while simultaneously activating NLRP3 makes them a potentially powerful anticancer agent for this Aggressive fatal disease." (PMID 37715239, 2023). "The analyzed data showed a close relationship between NLRP3 inflammasomes and carcinoma susceptibility, progression, and prognosis." (PMID 36902299, 2023). "Because there is a clear association between EGFR and NLRP3 in cancer cells, we examined EGFR-associated NLRP3 inflammasome activation in astrocytes in this study." (PMID 36341365, 2022). "In some cancers, the activation of NLRP3 causes a worse prognosis and in some cancers, NLRP3 increases chances of survivability." (PMID 35877745, 2022). "And the process of pyroptosis in various human cancer types was associated with NLRP3-related signaling pathways and NF-κB signaling pathway." (PMID 35242200, 2022). "Andrographolide can also inhibit NLRP3 activation by stimulating mitophagy, a process that is negatively correlated with the inflammasome, in colitis-associated cancer." (PMID 35754962, 2022). "Our previous study also provided evidence of NLRP3 activation being associated with cancer cell growth." (PMID 36012769, 2022). "Continual investigations on the interconnection between Nrf2 and NLRP3 inflammasome will deepen our understanding of the regulatory mechanism associated with cancer cell pyroptosis." (PMID 36387211, 2022). "Since an aberrant activation of the NLRP3 inflammasome is implicated in cancer initiation, there is great clinical interest in the development of potential inhibitors of NLRP3 inflammasome." (PMID 33840390, 2021). "Aberrant NLRP3 activation has divergent roles in the pathogenesis of inflammation-associated diseases such as cancer, as it can have both protumorigenic and antitumorigenic effects in a context-dependent and tissue-specific manner." (PMID 34064909, 2021). "Consistently, a mice model with NLRP3 deficiency showed the protection roles against cancer progression." (PMID 34747716, 2021).
cancer (continued). "Such auto amplification of IL-1β is found to involve NLRP3 inflammasome activation in cancer-associated macrophages." (PMID 34588926, 2021). "Thymoquinone has also been tested in vivo for NLRP3 associated actions in a murine model of cancer cell shift." (PMID 34443594, 2021). "Nod-like receptor protein 3 (NLRP3) is one of the most well studied inflammasomes among the families and its dysregulation is associated to cancer development." (PMID 32486083, 2020). "Further studies will be required to understand the association between genetic polymorphisms or differential expression of NLRP3 inflammasome and clinical features of cancer." (PMID 32733479, 2020). "Mice that express the truncated form of UVRAG, which is observed in cancer, were deficient in starvation‐ and LPS‐induced autophagy, and enhanced inflammation in a colitis‐associated cancer model due to NLRP3 inflammasome activation." (PMID 32745353, 2020). "The production of ROS has been associated with cancer promotion and is implicated in the regulation of NLRP3 inflammasome." (PMID 32435622, 2020). "NLRP3 inflammasome regulates the activation of pro-inflammatory cytokines that can have strong effects (protective and pathogenic are both reported) on cancer." (PMID 32226386, 2020). "NLRP3 plays a key role in inflammation, and activation of NLRP3 inflammasome has been linked to inflammation-induced cancer." (PMID 32435622, 2020). "In HNSCC, NLRP3 inflammasome is found upregulated in carcinoma tissues and associated with carcinogenesis and cancer stem cells (CSCs) self-renewal activation." (PMID 32733479, 2020). "In particular, the NLRP3 inflammasome has been implicated in cancer development, given its ability to activate the pro-inflammatory cytokines IL-1β and IL-18 which cause metabolic, inflammatory, hematological, and immune effects." (PMID 33014808, 2020). "NLRP3 plays a vital role in inflammation, and activation of NLRP3 inflammasome is associated with inflammation-induced cancer." (PMID 33603669, 2020). "The results show that the deficiency of NLRP3 inflammasome components in macrophages leads to suppression of metastatic potential of cancer cells by reducing migration and invasion." (PMID 31439870, 2019). "SNPs of NLRP3 greatly influence pathogenic challenges and lead to disease outcome, such as autoimmune diseases, cardiovascular diseases, and malignant tumors." (PMID 31428046, 2019). "Consistent with our opinion, Guo and colleagues reported that mitophagy induction was responsible for Andro-mediated suppression of NLRP3 inflammasome activation in colitis-associated cancer." (PMID 31416289, 2019). "The most studied and best characterized inflammasome, NLRP3, is an emerging, key player in the development and progression of cancer, and an increased expression of NLRP3 has been associated with multiple cancer types." (PMID 30631327, 2018). "Conversely, in the IL-18 deficient AOM/DSS murine model the cancer burden increased mirroring NLRP3 and caspase-1 deficient mice." (PMID 30447690, 2018). "NLRP3 deficient mice show reduced cancer invasion and tumorigenesis through a reduction in NK cell proliferation and CXCL9 chemokine secretion." (PMID 30447690, 2018). "NLRP3 inflammasome functioned as a negative regulator of tumorigenesis during colitis-associated cancer." (PMID 28865486, 2017). "Genetic SNPs of the genes associated with NLRP3 inflammasome were found to be related to several cancers." (PMID 29312552, 2017). "Therapeutic ketosis reduces circulating inflammatory markers, and ketones directly inhibit the NLRP3 inflammasome, an important pro-inflammatory pathway linked to carcinogenesis and an important target for cancer treatment response." (PMID 28250801, 2017). "Given that P2X7 is a major positive regulator of the NLRP3 pathway, it is tempting to speculate that at list part of Foxp3 positive cells could belong to the subclass of Foxp3+ RORγt + IL17+ cells which were recently associated with NLRP3 activation in cancer." (PMID 40759630, 2025).